SLC6A4 (solute carrier family 6 member 4)
Diseases named in the same sentence as SLC6A4 in open-access papers (continued):
Sharing a sentence is not in itself a finding about the gene and the disease.
depression (continued). "This may account for the lack of associations observed between depression and SLC6A4 methylation in our study." (PMID 30180828, 2018). "Thus, the role of SLC6A4 and its (dys)regulation has been a major focus of depression research." (PMID 30180828, 2018). "A common variant (polymorphism) located in the promoter region of the gene (SLC6A4) encoding the transporter, the serotonin transporter-linked polymorphic region (5-HTTLPR), has been widely studied with regard to individual differences in trait neuroticism, anxiety, and depression." (PMID 25995833, 2015). "However, when hierarchical diagnostic criteria for depression was used as the output variable, the SS SLC6A4 genotype (but not BDNF) was a predictor of major depression (Wald's statistic 5.8, P = 0.016, CI = 1.1–2.7)." (PMID 24683520, 2014). "qPCR results showed that knockdown of Homer1 improved the expression of inflammation‐related markers IL‐1β, TNF‐α, IL‐10, and depression‐related markers ERCCL2, SLC6A4, and GAD1 in primary neurons, both in the PTSD group and in the TBI+Hcort group." (PMID 39665190, 2025). "In the field of depression, 5-HT-related genes (e.g., HTR1A, HTR2A, and SLC6A4) and their SNPs are also the predominantly researched pharmacodynamic genes." (PMID 37581520, 2024). "This study predicted that linalool, p-cymene, α-terpinene, terpinen-4-ol, and α-terpineol primarily contribute to CBEO’s anti-depressant effect, mainly via interactions with OPRM1, PTGS2, ESR1, SLC6A4, DRD2, and NR3C1, the six depression-related targets." (PMID 38567354, 2024). "Furthermore, the rs25531 SNP of the SLC6A4 gene, which may also affect gene expression, has not been associated with depression risk in PD in two studies." (PMID 37374342, 2023). "Therefore, it seems that apart from the L/S alleles, other polymorphisms of the SLC6A4 gene may not play a significant role in the onset of depression in PD." (PMID 37374342, 2023). "A review on DNA methylation in depression demonstrated a connection between depression and methylation of BDNF and NR3C1 genes, while the correlation of SLC6A4 with depression was conflicted." (PMID 35807931, 2022). "These genes are involved in the complex pathological mechanism of depression, including the neurotransmitter system (e.g., HTR2A and SLC6A4), neurotrophin (e.g., BDNF), hypothalamic-pituitary-adrenal (HPA) axis (e.g., CRH), and inflammation (e.g., IL6, TNF)." (PMID 36072347, 2022). "Five important depression targets identified using the network map (GRIN2B, GRIN2A, DRD2, SLC6A4, and MAOA) and twenty-one related active compounds were selected for molecular docking." (PMID 33746756, 2021). "SLC6A4 5-HTTLPR + rs25531 locus was significant in the recessive model (p = 0.024), and also affected the severity of symptoms of depression (p = 0.044) and personal anxiety (p = 0.029)." (PMID 34199792, 2021). "Concluding, we observed a significant association between lower levels of methylation the BDNF and SLC6A4 gene promoters and presence of MDD or life history of depression in patients with TLE." (PMID 34912196, 2021). "The 6 top blood biomarkers with the strongest overall CFE for tracking and predicting both depression and mania, hence bipolar mood disorders, after the first four steps were NRG1, DOCK10, GLS, PRPS1, TMEM161B, and SLC6A4." (PMID 33828235, 2021). "In this study, we estimated the contribution of SLC6A4 (5HTT), HTR1A, HTR2A, HTR1B, SLC6A3 (DAT1), DRD4, DRD2, COMT, and BDNF genes to the suicidal behavior and severity of symptoms of depression and anxiety in the East-Slavic population of Russia." (PMID 34199792, 2021). "Studies over the past years suggest that the methylations of some specific genes such as BDNF, SLC6A4, and NR3C1 play an important role in the development of depression." (PMID 33101076, 2020). "Candidate genes of DNA methylation, such as NR3C1, SLC6A4, and BDNF, have been regarded as potential biomarkers of depression." (PMID 32256396, 2020).
depression (continued). "Early candidate genes studied in relation to brain phenotypes included the sodium-dependent serotonin transporter gene (SLC6A4) in individuals with anxiety and depression and the catechol-O-methyltransferase gene (COMT) in individuals with schizophrenia." (PMID 29179742, 2017). "A landmark discovery in this respect was the finding that the association of a polymorphism in the promoter region of the serotonin transporter gene (SLC6A4, commonly known as 5-HTT) with depression is influenced by stressful life events." (PMID 23966957, 2013). "The SS genotype of 5-HTTLPR restricts the transcriptional activity of the promoter, leading to a decrease in the level of transcription of the 5-HT transporter protein gene (SLC6A4) and a reduction in 5-HT reuptake, which can contribute to the development of depression." (PMID 38404466, 2024). "Furthermore, variants of genes like SLC6A4 and ANK3 have also been associated with a higher risk of depression or bipolar disorder when present in two copies, but not when present in only one copy, suggesting that heterozygosity for such variants may confer protection against depression." (PMID 37124257, 2023). "SLC6A4 methylation was not related to depression severity, age at depression onset or SLEs in the entire group, but positively related to depression severity in women." (PMID 33765975, 2021). "A number of individual top biomarkers are known to be modulated by medications in current clinical use for treating depression, such as by lithium (NRG1, PRPS1, CD47), antidepressants (SLC6A4, DOCK10, NRG1, CD47) and the nutraceutical omega-3 fatty acids (GLO1, SLC6A4, CD47, GLS, HNRNPDL)." (PMID 33828235, 2021). "Two non-motor symptoms including depression and intellectual impairment were analyzed in association with 5-HTTLPR and rs25531 variants of SLC6A4 in the PD patients." (PMID 31024427, 2019). "The objectives of the present study were to verify whether older women with anxiety disorder/depression differ from control subjects according to DNA methylation and genotypes at SNVs in BDNF, OXTR, SLC6A4, and APOE." (PMID 26175754, 2015). "These differing results highlight that there is no convincing evidence that methylation in the SLC6A4 gene contributes to sex differences in prevalence of depression." (PMID 25781010, 2015). "When their mother had few or no depression symptoms, LL children did extremely well—no other group regardless of SLC6A4 genotype or mother's mood had mean scores that were as high." (PMID 24130516, 2013). "The literature is not conclusive on how methylation of SLC6A4 differs in depression." (PMID 36503539, 2022). "The docking results of GABRA1 with naringenin and hesperidin, HCRTR1 with naringenin-7-O-glucoside, poncirenin and genipin 1-gentiobioside, and luteolin with SLC6A4, GLO1, MAOB and MTNR1A may clarify the mechanism of action of ZZHPD in treating insomnia and depression." (PMID 35095537, 2021). "Therefore, SLC6A4 methylation does not seem strongly related to depression, which questions the usefulness of SLC6A4 methylation as biomarker for depression onset." (PMID 33765975, 2021). "Indeed, a number of recent studies have reported that genes known to be implicated in depression, such as SLC6A4, NR3C1 and BDNF, are differentially methylated in peripheral blood and/or buccal cells of individuals with depression, compared to those without." (PMID 29070016, 2017). "In humans, a repeat length polymorphism (5HTTLPR) in the transcriptional control region of the 5-HTT gene (SLC6A4) was found, resulting in allelic variation of 5-HTT expression and function, and associated traits of negative emotionality including anxiety and depression." (PMID 25784864, 2015). "The node degrees of IL6, nitric oxide synthase 3 (NOS3), solute carrier family 6 member 4 (SLC6A4), estrogen receptor (ESR1), and tumor necrosis factor (TNF) were greater than 10, suggesting that these targets could play important roles in the effects of AL on depression." (PMID 36431060, 2022).
depression (continued). "Furthermore, SLC6A4 methylation was not included in the model prediciting age at depression onset." (PMID 33765975, 2021). "However, if the lack of a direct association between SLC6A4 or the 5-HTT and depression replicates in future studies, the mechanism of action of SSRIs and the role of the serotonin system in the development and maintenance of depression as a whole would need to be re-discussed." (PMID 33765975, 2021).
Anxiety (235 papers, 2007 to 2025). Intense feelings of nervousness, tension, or panic often arise in response to interpersonal stresses. "The SLC6A4 LL variant moderated effects of maternal anxiety on adolescent suicide ideation risk cognition." (PMID 39910899, 2025). "This study investigated the relationship between 5-HTTLPR polymorphism in the SLC6A4 gene, personality traits, anxiety, and alcohol use disorder." (PMID 40422201, 2025). "Epigenetic markers like SLC6A4 or OXTR methylation can predict risk for MDD or anxiety after trauma and individual resilience profiles." (PMID 41234420, 2025). "The short mutant allele S is supported by lower transcriptional activity and enhanced anxiety in the SLC6A4 gene than the long mutant allele (l)." (PMID 39590895, 2024). "A polymorphism of the gene SLC6A4, encoding the serotonin (5HT) transporter (SERT), has been linked to the etiology of anxiety-related traits in humans and SLC6A4 knockout mice exhibit an anxious-like phenotype." (PMID 40656087, 2024). "The SLC6A4 short/short allele amplifies risk of anxiety‐related mental illness when children experience food insecurity." (PMID 38361316, 2024). "This was motivated by a recent marmoset study showing an SLC6A4 haplotype associated with heightened anxiety and reduced insula 5‐HT2AR binding." (PMID 32697408, 2020). "Individuals with the short allele of the SLC6A4 gene-linked polymorphic region (5-HTTLPR) are more likely to present with greater anxiety, impairments in social interaction, and deficits in emotional regulation." (PMID 30498565, 2018). "Distribution of genotypes and alleles frequency of the polymorphism in the 5-HTTLPR (SLC6A4) promoter region, and intensity of anxiety as a state acc." (PMID 25547397, 2014). "The objective of this study is to analyze how the mood and the level of anxiety of postmenopausal women are related to the 5-HTTLPR (SLC6A4) polymorphism and the 30-bp VNTR polymorphism in the MAO A promoter region." (PMID 25547397, 2014). "Nevertheless, it showed that respondents with s/s genotype of the 44-bp polymorphism in the 5-HTT (SLC6A4) promoter region had the highest average anxiety levels both as a state and as a trait." (PMID 25547397, 2014). "Nevertheless, it showed that respondents with the s/s genotype of the 44-bp polymorphism in the 5-HTT (SLC6A4) promoter region had the highest average anxiety levels both as a state and as a trait." (PMID 25547397, 2014). "The SLC6A4 gene, which encodes the sodium dependent, high-affinity, low-capacity serotonin transporter, regulates extracellular and synaptic serotonin concentrations, and has been associated with anxiety-related temperamental dimensions, and depression." (PMID 38705984, 2024). "Likewise, other genes related to 5-HT signaling, such as htr1a and slc6a4, have also been linked to anxiety-related defensive behavioral responses in rodents." (PMID 38705984, 2024). "In conclusion, our findings suggest that epigenetic marks at the SLC6A4 gene, responsive to environmental stressors, might play a role in EDs and/or associated phenotypes, including anxiety and increased stress reactivity." (PMID 36678277, 2023). "The effect of DRD4 and SLC6A4 polymorphisms on anxiety adjusting for other covariates." (PMID 33784353, 2021). "Repetitive CRHR activation in BNST, caused anxiety, increases the genes expression of the serotonergic systemin DR, including Tph2 (a gene of a key serotonin synthesisenzyme) and Slc6a4 (a gene encoding a serotonin transporter(SERT))." (PMID 34901719, 2021). "Finally, we assessed the moderating influence of candidate genes whose level of methylation is associated with the Nr3c1 genotype on anxiety-like behavior: Ank3, Avp, Avpr1a, Avpr1b, Bdnf, Cacna1c, Cyp11b1, Cyp11b2, Fkbp5, Hsd11b1, Igf2, Morc1, Nr3c1, Oxt, Oxtr, Pclo, Slc6a4." (PMID 30655507, 2019). "Associations of the 5-HTT (SLC6A4) and the MAO-A genotypes with the severity of anxiety symptoms as measured by the STAI." (PMID 40416692, 2025).
Anxiety (continued). "(2021) discovered that the SLC6A4 gene plays a moderating role in the relationship between chronic stress and anxiety among individuals in the age range of 14 to 21 years." (PMID 39910899, 2025). "SLC6A4 regulates serotonin availability in the brain, impacts mood, emotion, anxiety, and stress regulation, and is the main target of SSRIs used in treating MDD and anxiety disorders." (PMID 41234420, 2025). "Increased expression of tph2, htr1a, and slc6a4 in the cDRD of HFD-fed rats is consistent with previous studies implicating the cDRD in chronic (even lifelong) anxiety-like states, and vulnerability to future stress exposures in adulthood." (PMID 38705984, 2024). "Overall, our results show that a HFD increases tph2, htr1a and slc6a4 mRNA gene expression in areas of the DR, including subregions (e.g. cDRD) involved in the regulation of anxiety-related behaviors." (PMID 38705984, 2024). "(2021) discovered that the SLC6A4 gene plays a moderating role in the relationship between chronic stress and anxiety among individuals in the age range of 14–21 years." (PMID 38361316, 2024). "Our results show animals fed a HFD had higher expression of tph2, htr1a and slc6a4 in the anxiety-related cDRD subregion." (PMID 38705984, 2024). "Here we conducted a nine-week HFD protocol in male rats, followed by an analysis of the gut microbiome diversity and community composition, brainstem serotonergic gene expression (tph2, htr1a, and slc6a4), and anxiety-related defensive behavioral responses." (PMID 38705984, 2024). "All models evaluating the association between SLC6A4/TPH2 methylation and measures of early stress, anxiety or depressive symptoms and including cells proportions showed a significant association between lymphocytes proportions and CpGLV." (PMID 38802956, 2024). "The SLC6A4 gene has been indicated as a moderator of the effects of chronic stress on anxiety in adolescents aged 14–21." (PMID 38361316, 2024). "Specifically, we sought to investigate changes in weight, mood-related behavior (depression and anxiety), and the differential mRNA expression of specific serotoninergic system genes (Slc6a4, Htr1a, and Htr2c) in male Wistar rats." (PMID 38398814, 2024). "For all future hospitalizations with anxiety in the independent test cohort SLC6A4, increased in expression in high anxiety, had an OR of 1.21 (p = 0.01) across all subjects." (PMID 36878964, 2023). "Multiple high-confidence ASD risk genes associated with anxiety were dysregulated in our RNA-seq data including TMLHE and GRID2, DNAH10, GRIA1, SLC6A4, and IGF1." (PMID 37486945, 2023). "A key candidate gene in the study of anxiety and stress-related disorders is the serotonin transporter (5-hydroxytryptamine transporter or 5-HTT) gene (also known as SLC6A4 (Solute Carrier Family 6 Member 4))." (PMID 37531334, 2023). "COMT, SLC6A4, SLC6A3, and IL-12b gene mutations were also associated with melanoma sites and TNM stage, anxiety, and QOL." (PMID 36405903, 2022). "Animal studies using constitutive Slc6a4 knockout mice showed increased anxiety-like phenotypes in various behavioral tests." (PMID 33574244, 2021). "We observed an effect of SLC6A4 5-HTTLPR + rs25531 locus on depressive and personal anxiety symptoms and an effect of DRD4 48 bp VNTR-polymorphism on situational anxiety." (PMID 34199792, 2021). "The specific genetic influence of SLC6A4 on anxiety sensitivity has also been well-demonstrated, and this effect is modified by the severity of childhood trauma." (PMID 35153849, 2021). "Significant differences were observed in the distribution of 5-HTTLPR genotypes, SLC6A4 tri-allelic-phased genotype, and DRD4-Exon III VNTR genotypes/alleles between patients with anxiety symptoms versus those with normal/borderline conditions (p<0.05)." (PMID 33784353, 2021). "SLC6A4 regulates synaptic concentrations of serotonin, indirectly influencing perception and anxiety-related behavior." (PMID 32770228, 2020).